CCND1 (cyclin D1)
Diseases named in the same sentence as CCND1 in open-access papers (continued):
Sharing a sentence is not in itself a finding about the gene and the disease.
lung carcinoma (continued). "Knockdown of CCND1 was found to prolong survival by attenuating FGF19-induced cell proliferation in a murine lung cancer model." (PMID 35463335, 2022). "The development of lung cancer is related to decreased miR-3940-5p accumulation in cancer cells via targeting ubiquitin-specific peptidase 28 and cyclin D1 to suppress cancer progression." (PMID 35235752, 2022). "DG demonstrated the anti-lung cancer activity by arresting the cell cycle in G1 via increasing the p21, p27, cyclin D1, cyclin E, and decreasing Cdc2, cyclin A, and B1 proteins expression in A549 human lung cancer cells." (PMID 35836974, 2022). "In another study, 48 h of exposure of two human lung carcinoma cell lines, H292 and H1299, to PM resulted in an S-phase block of the cycle as a result of cyclin D1 downregulation." (PMID 36008994, 2022). "Lung cancer cells treated with doses till 6 μM PD, showed a dose-dependent reduction in Bcl-2 and cyclin D1 levels as well as an increase in Bax, leading to cell cycle arrest at the S phase." (PMID 36364001, 2022). "In terms of other genes evaluated in this study, a previous study demonstrated a role played by Fib-3 on Ccnd1 expression levels in lung cancer cells." (PMID 35795376, 2022). "In human lung cancer and pancreatic cells shikonin suppressed cell proliferation through modulating the expression of cell cycle regulators like cyclin D1 or cMyc." (PMID 35820864, 2022). "Cyclin D1 plays a role in the development and progression of numerous malignancies, including breast, esophageal, bladder, and lung cancers." (PMID 36671388, 2022). "In contrast, miR-3940-5p suppresses lung cancer progression by downregulating multiple oncogenes, such as ubiquitin-specific peptidase-28 and cyclin D1." (PMID 35235752, 2022). "Previously, ARAP1-AS1 was reported to be upregulated in lung cancer and ARAP1-AS1 knockdown significantly suppresses the proliferation of lung cancer cells and induce G0/G1 cell cycle arrest by reducing the expression of cell cycle-related protein cyclin D1." (PMID 35291911, 2022). "Analysis of the effects of CCND1 expression on lung cancer cell migration and invasion showed that CCND1-OE enhanced cell migration and invasion activities." (PMID 35246017, 2022). "CCND1 upregulation is responsible for the enhanced lung cancer progression and liver metastases in vivo." (PMID 35246017, 2022). "Through mining the two online mRNA datasets and GO analysis, we discovered that CCND1 is one of the overlaps, implying it as a possible target in lung cancer." (PMID 35246017, 2022). "In conclusion, we found that CCND1 is increased in lung cancer in a NF-κB nuclear translocation-dependent manner, which promotes lung cancer cell proliferation and oncogenic activity by inducing the PI3K/AKT signaling pathway." (PMID 35246017, 2022). "HER2/HER3 were also found to be upstream transcription factor of CCND1 in lung cancer which is reported to enhance EGFR-TKI resistance." (PMID 35365622, 2022). "Here, we established that CCND1 is overexpressed in clinical lung cancer specimens and various lung cancer cells." (PMID 35246017, 2022). "Detection of CCND1 expression in lung cancer cells revealed that CCND1 was generally elevated in lung cancer cells." (PMID 35246017, 2022). "MiR-95-3p can directly regulate cyclin D1 levels, with lower levels of cyclin D1 leading to lower invasiveness, colony formation, and a proliferation of lung cancer cell lines with brain tropism." (PMID 35884446, 2022). "CCND1 overexpression was found in lung cancer cells and tissues, and enhanced the cell proliferation, migration, invasion and cell cycle arrest of lung cancer cells." (PMID 35246017, 2022).
lung carcinoma (continued). "In the present study, we aimed to evaluate the overexpression of CCND1 in lung cancer cell growth in vitro and in vivo and explore the molecular mechanisms associated with NF-κB." (PMID 35246017, 2022). "As a result, we postulated that another transcription factor exists to regulate the CCND1 transcription in lung cancer." (PMID 35246017, 2022). "KDM5A is overexpressed in lung cancer tissues and facilitates cell proliferation, invasion, and metastasis of lung cancer via inhibiting the expression of p27 and upregulating cyclin D1, and ITGB1." (PMID 33596982, 2021). "Some studies have shown that CDK4 and cyclin D1 expression is correlated with the presence of KRAS mutation in lung tumors, and a synthetic lethal interaction occurs between KRAS and CDK4 in lung cancer tumor progression." (PMID 34309585, 2021). "On the one hand, we found that licorice down-regulates CDK4-Cyclin D1 complex, resulting in G0/G1 phase arrest and increased PD-L1 levels in lung cancer cells." (PMID 34641869, 2021). "Treatment of lung cancer cells with luteolin decreased the expression of cyclin D1 and cyclin D3, cell cycle markers compared with control." (PMID 33982869, 2021). "So, we concluded that licorice induces G1 cell-cycle block in lung cancer cells by inhibiting CDK4-Cyclin D1 complex, which in turn increase antigen presentation and results in intra-tumoral CD8+ T cell infiltration." (PMID 34641869, 2021). "Consistently, the cell cycle-and apoptosis-related protein expressions of mTOR, STAT3, Bcl-2, and cyclin D1 significantly increased in A549 lung cancer cells after treatment with 100 ng/ml leptin." (PMID 33708630, 2021). "In the A549 lung cancer cell line, BB inhibited the expression of Cyclin D1 leading to G1 phase cycle arrest." (PMID 34771481, 2021). "Our detailed investigation shows that licorice induces G1 cell-cycle arrest in lung cancer cells by inhibiting CDK4-Cyclin D1 complex, which in turn increases antigen presentation and results in intra-tumoral CD8+ T cell infiltration but increase PD-L1 levels." (PMID 34641869, 2021). "Despite the strong proof of concept, the study needs to further investigate the role of Prox1 in the proliferation, migration, and invasion of lung cancer cells, and the role between Rho protein and Cyclin D1 need to be further demonstrated." (PMID 34183992, 2021). "Herein, we report that VRK1 is post-transcriptionally upregulated in lung cancer cells, leading to the increased expression of CCND1." (PMID 34071140, 2021). "Taken together, our work supports the notion that Cyclin K exerts its biological functions primarily through regulating Cyclin D1 in lung cancer cells." (PMID 33042275, 2020). "Similar to other types of lung cancer, amplifications or deletions of genes in the cell-cycle pathway (CCND1, CDKN2A, and RB1) were frequently identified in PSC." (PMID 32985499, 2020). "ART restricted proliferation of lung cancer cells in the G0/G1 phase by decreasing Cyclin D1, Cyclin E, CDK2, and CDK4 expression." (PMID 33316936, 2020). "Similar to cyclin D1, the c-myc oncogene is known to play a major role in the development of cancer and is dysregulated in most malignancies, including lung cancer." (PMID 33158043, 2020). "UBE1L‐mediated ISGylation of cyclin D1 in lung cancer cells reduces detectable protein levels with an antiproliferative effect." (PMID 31820845, 2020). "It has been reported that transcriptional activation of cyclin D1 via HER2/HER3 contributed to EGFR‐TKI resistance in lung cancer cells." (PMID 32898333, 2020). "Cordycepin can bind to the AR3 to inhibit cell proliferation by inactivating glycogen synthase kinase (GSK)-3β/β-catenin signaling pathway, and subsequently suppressing cyclin D1 and c-myc expression in melanoma and lung carcinoma cells." (PMID 33172093, 2020).
lung carcinoma (continued). "A number of studies have demonstrated that CCND1 is a key driver of malignant transformation and is frequently overexpressed in lung cancer which attributed to cancer cell proliferation." (PMID 32180726, 2020). "Collectively, these results indicate that Cyclin K interacts with and promotes the stabilization of β-catenin, thereby upregulating the expression of Cyclin D1 and facilitating DNA repair in lung cancer." (PMID 33042275, 2020). "Si-CCND1 proved significant antitumor effect in the genetic background of FGFR1 amplified lung cancer." (PMID 32380883, 2020). "Previous studies demonstrated that FOXK2 suppressed the growth of lung cancer cells by targeting cyclin D1 and CDK4 and also influenced CDKs, which linked it to the regulation of the cell cycle." (PMID 33251211, 2020). "More importantly, we show that Cyclin D1 is the major effector that mediates the biological functions of Cyclin K in lung cancer." (PMID 33042275, 2020). "CCND1 is overexpressed in epithelial ovarian cancer, colorectal cancer, liver cancer, gastric cancer, nasopharyngeal cancer, and lung cancer, leading to changes in the cell cycle, which, in turn, give rise to the occurrence of tumors." (PMID 32095323, 2020). "Taken together these data highlight a correlation between cyclin D1/CDK4 expression and KRAS mutation in lung ADC, suggesting enhanced activation of CDK4/Cyclin D in KRAS mutant lung cancer." (PMID 32104498, 2020). "It was also found that downregulation of E2F7 by miRNA-302a/d decreased proliferation of hepatocellular carcinoma cells and significantly inhibited stemness of lung cancer stem cells by targeting the E2F7/AKT/β-catenin/CCND1 signaling pathway." (PMID 33061852, 2020). "In the present study, we identified miR-193b-3p and -5p as a new dual-strand tumor suppressor, which inhibits the proliferative and metastatic potential of lung cancer by suppressing common targets, including CCND1, AJUBA, and HEG1." (PMID 31262974, 2019). "In previous reports, we also revealed that cyclin D1 is a critical regulator of aggressiveness of lung cancer, which is responsible for brain metastasis of lung cancer cells." (PMID 31262974, 2019). "KAT2A over expression increases the extent of histone acetylation by interacting with E2F1, cyclin D1, and E1 promoters to promote the proliferation of lung cancer cell lines." (PMID 31828117, 2019). "In fact, IL-6/STAT3 signaling has been shown to suppress lung cancer initiation while promoting cancerous cell proliferation, migration, and disease progression by positively modulating the induction of cyclin D1." (PMID 31547048, 2019). "Expression of cell cycle regulatory proteins CDK4, CDK6, and cyclin D1 was significantly decreased in ApoE knockdown lung cancer cells." (PMID 31275318, 2019). "It was revealed that miR-193b-3p and -5p regulate malignant phenotypes of lung cancer through the suppression of their common target genes (i.e., CCND1, AJUBA, and HEG1)." (PMID 31262974, 2019). "By inducing cyclin D1 upregulation via the c-Fos/c-Jun pathway, IL-7 promotes the proliferation of lung cancer cells." (PMID 31061414, 2019). "Our results show that tetracenomycin X only activates the phosphorylation levels of p38 and c-JUN proteins in lung cancer cells, which leads to the downregulation of cyclin D1." (PMID 30669360, 2019). "STX-0119 inhibited activated STAT3 and the expression of STAT3-regulated oncoproteins such as c-Myc, cyclin D1, and survivin in lung cancer cells." (PMID 32257917, 2019). "PDLIM2 deletion increased while its expression decreased expression of cell growth genes, including Bcl-xL and Cyclin D1 in lung cancer cells." (PMID 31757943, 2019). "The proliferation and invasion of lung cancer cells can be promoted by regulating the expression of cyclin D1." (PMID 30279365, 2018).
lung carcinoma (continued). "Ectopic expression of HOXA4 led to an obvious decrease in the protein levels of downstream effectors of the Wnt pathway (β-catenin, Cyclin D1, c-Myc, and Survivin), which are involved in the development of lung cancer." (PMID 29700285, 2018). "The C8-ceramide-induced treatment modulated the levels of SOD1 and cyclin D1 in H1299 lung cancer cells on a protein level, which was examined by Western blotting in the present study." (PMID 30279365, 2018). "In the present study, DDA1 was shown to be responsible for lung cancer cell G1/S transition and cell proliferation through the regulation of cyclin D1, cyclin D3, cyclin E1 and cyclin B1 expression." (PMID 28211159, 2017). "Activation of cell membrane nAChRs via α7 and β2 subunits is associated with increased expression of cyclin D1 and phosphorylation of ERK1/2, inhibition of mPTP opening and resistance to H2O2-induced apoptosis in oral and lung cancers." (PMID 29088845, 2017). "Taken together, these results indicate that DDA1 promotes the progression of lung cancer by regulating the cell cycle, especially S phase, and cyclins such as cyclin D1/D3." (PMID 28211159, 2017). "The relative expression levels of CD44, cyclin-D1, and c-myc were significantly decreased by atranorin treatment in lung cancer cells." (PMID 28811522, 2017). "Cyclin D1 and cyclin E are important members of cyclin family, which are upregulated in human lung cancer cells and regulates the progression of the cell cycle by controlling G1/S transition." (PMID 28977927, 2017). "The damages of retinoblastoma-Cyclin D1-p16 cell cycle pathway are important in the carcinogenesis of lung cancer." (PMID 27281096, 2016). "Loss of UBE1L is a common event in lung carcinogenesis, and the UBE1L gene suppressed lung cancer growth by preferentially inhibiting cyclin D1." (PMID 27028764, 2016). "TRIM29 can promote lung cancer proliferation through NF-kB induced up-regulation of cyclin D1 and c-Myc." (PMID 27145374, 2016). "Relative expression levels of CD44, cyclin D1, and c-myc were significantly decreased by (+)-usnic acid treatment in lung cancer cells to different extents." (PMID 26751081, 2016). "In non-small cell lung cancer, miR-16 is frequently deleted and downregulated, and miR-16 has been shown to regulate the cell cycle of lung cancer cells by regulating CCND1." (PMID 26655091, 2016). "We show for the first time that miR-326 directly targets and regulates the full-length 3′-UTR of the human CCND1 mRNA, which is up-regulated in many cancers, including lung cancer." (PMID 26840018, 2016). "Ectopic expression of miR-329 in lung cancer cell lines substantially repressed cell growth as evidenced by cell viability assay, colony formation assay and BrdU staining, through inhibiting cyclin D1, cyclin D2 and up-regulatiing p57(Kip2) and p21(WAF1/CIP1)." (PMID 26909600, 2016). "The CCND1 promoter we had previously identified as a transcriptional target of ErbB380kDa in the H358 lung carcinoma cell line, was found significantly enriched in LNCaP and PC3 cell lines and was considered further as positive control for ErbB380kDa binding." (PMID 27191720, 2016). "We find that miR-134 directly targets 3′-UTR of human CCND1 mRNA, which is up-regulated in many cancers, including lung cancer." (PMID 27166267, 2016). "Consistent with in vitro metastatic cells, the levels of miR-95-3p, pri-miR-95, and ABLIM2 mRNA were decreased in brain metastatic tissues compared with lung cancer tissues and higher cyclin D1 expression was involved in poor prognosis." (PMID 25971210, 2015). "Cyclin D1 is a well-known oncogene that is frequently overexpressed in various cancers including lung cancer." (PMID 25971210, 2015). "We also found that the levels of miR-95-3p and its host gene, actin binding LIM protein family member 2 (ABLIM2), are lower in brain metastatic lesions than in primary lung cancer, and cyclin D1 expression correlated with poor prognosis." (PMID 25971210, 2015).
lung carcinoma (continued). "The down-regulation of cyclin D1 by vorinostat was comparable to a siRNA-mediated knockdown of cyclin D1 in A549 cells, but vorinostat in the presence of benzo[a]pyrene showed a differential effect in different lung cancer cell lines." (PMID 26681199, 2015). "Highly expression of cyclin D1 protein has been displayed in invasive lung cancer cells, and is correlated with low survival rate and poor prognosis of lung cancer patients." (PMID 25946558, 2015). "In murine and human lung cancer cell lines and genetically engineered mouse lung cancer models, Vorinostat reduced cancer cell growth, cyclin D1 and cyclin E expressions, but increased p27 expression, histone acetylation and apoptosis." (PMID 25738536, 2015). "Cyclin D1 is one of the most important cell cycle regulatory proteins, playing pivotal roles in the development of a subset of human cancers including lung cancer." (PMID 25863539, 2015). "YB-1-regulated Cyclin D1 transcription was recently reported in lung cancer cells, and re-introduction of Cyclin D1 in YB-1-silenced osteosarcoma cells resumed the proliferative capacity of the cells." (PMID 25993060, 2015). "To verify that miR-95-3p suppresses cyclin D1 expression, we transfected various lung cancer cells with pre-miR-95- 3p." (PMID 25971210, 2015). "Published data showed that Cyclin D1 was a downstream target of RBP2 in lung cancer, so we tried to testify this in GC." (PMID 25015565, 2014). "Since cyclin D1 is present in the same chromosomal arm as YAP1 but in 11q13 and CCND1 is frequently amplified in lung cancer, we used one probe specific for cyclin D1 gene and another probe specific for YAP1 gene or FISH analyses." (PMID 24810989, 2014). "We also found that miR-545 caused cell cycle arrest at the G0/G1 phase and induced cell apoptosis in lung cancer cells by targeting cyclin D1 and CDK4 genes." (PMID 24505359, 2014). "The aim of this study is to explore the relationship between Brucine and the proliferation in human lung cancer cell line PC-9, and the effect of it on the expression of Cyclin D1 and Cyclin E." (PMID 24949683, 2014). "miR-545 inhibits the proliferation of lung cancer cells by repressing the expression of cyclin D1 and CDK4 genes." (PMID 24505359, 2014). "Brucine can inhibit the proliferation of human lung cancer cell line PC-9 mainly by blocking the cell cycle at G0/G1 via down-regulating the expression of Cyclin D1, Cyclin E." (PMID 24949683, 2014). "This suggests a possible involvement of NF-κB pathway in ATDC induced cyclin D1 and c-Myc up-regulation and cell proliferation in lung cancer cells." (PMID 23776433, 2013). "In our study, cell cycle arrest at G1 phase after ATDC knockdown in the 2 lung cancer cell lines (A549 and H1299) seems to be in keeping with corresponding down-regulation of cyclin D1 and c-Myc." (PMID 23776433, 2013). "A number of studies in lung cancer cells suggest that RhoA plays important roles in cyclin D1 and cell cycle progression." (PMID 23607551, 2013). "We have recently found that TRIM16 overexpression correlated with cell growth inhibition through effects on cyclin D1 and phospho-Rb in lung cancer cells." (PMID 22009481, 2012). "Earlier data from our laboratory has shown that P276-00, a Cdk inhibitor inhibits cyclin D1 and down regulates Cdk4 specific phosphorylation of RB at Ser780 (pRbSer780) along with up regulation of p27 and p21 in breast and lung cancer cell lines." (PMID 23075291, 2012). "A recent study supports the promise of co-targeting Cyclin D1 as a predictive and personalizing approach for lung cancer prevention and therapy." (PMID 23285263, 2012).